ITGA10 (integrin subunit alpha 10)
Description:
Integrin alpha-10/beta-1 is a receptor for collagen.
Synonyms: PRO827
Tractability: Antibody: its Gene Ontology location is reachable by antibodies, with high confidence; UniProt predicts a signal peptide or a membrane-spanning region.
Target class: Adhesion
Gene: Protein-coding gene on chromosome 1 (145,891,206 to 145,910,111, reverse strand). Ensembl gene ENSG00000143127.
Subcellular location: Membrane
Subcellular location (Human Protein Atlas): Endoplasmic reticulum
Pathways (Reactome):
Developmental Biology: CHL1 interactions
Extracellular matrix organization: Integrin cell surface interactions
Hemostasis: Platelet Adhesion to exposed collagen
Gene Ontology:
Molecular function: collagen binding involved in cell-matrix adhesion; collagen binding; signaling receptor activity
Biological process: cell-matrix adhesion; integrin-mediated signaling pathway; cell-cell adhesion; cell adhesion
Cellular component: integrin alpha10-beta1 complex; cell surface; integrin complex; plasma membrane; membrane
Genetic constraint (gnomAD): Loss-of-function variants: 98 observed, 139.07 expected, observed/expected ratio (o/e) 0.7, 90% interval 0.6 to 0.83. The upper end of that interval is the gene's LOEUF score, 0.83, which puts it in group 3 of 6, group 1 being the genes least tolerant of losing a copy. Missense variants: 1,284 observed, 1,465.7 expected, observed/expected ratio (o/e) 0.88, 90% interval 0.84 to 0.92. Synonymous variants: 498 observed, 568.05 expected, observed/expected ratio (o/e) 0.88, 90% interval 0.81 to 0.94.
Homologues: Orthologues: chimpanzee ITGA10 (99% identical), macaque ITGA10 (98% identical), pig ITGA10 (93% identical), rabbit ITGA10 (92% identical), dog ITGA10 (92% identical), guinea pig ITGA10 (90% identical), mouse Itga10 (88% identical), rat Itga10 (87% identical), tropical clawed frog itga10 (55% identical), zebrafish itga10 (53% identical), Drosophila melanogaster mew (20% identical), Caenorhabditis elegans ina-1 (20% identical), and 5 more. Paralogues in human: ITGA11 (44% identical), ITGA1 (35% identical), ITGA2 (34% identical), ITGAD (27% identical), ITGAM (27% identical), ITGAX (26% identical), ITGAL (26% identical), ITGAE (24% identical), ITGA6 (21% identical), ITGA9 (20% identical), ITGA7 (20% identical), ITGA5 (20% identical), and 5 more.
Diseases named in the same sentence as ITGA10 in open-access papers:
ITGA10 is named in the same sentence as 41 diseases in open-access papers, as found by Europe PMC text mining. Sharing a sentence is not in itself a finding about the gene and the disease. The quoted sentences say what the papers report.
osteosarcoma (8 papers, 2021 to 2026). A usually aggressive malignant bone-forming mesenchymal neoplasm, predominantly affecting adolescents and young adults. "ITGA10 is believed to drive osteosarcoma proliferation and chemotherapy resistance by mediating the PI3K/AKT pathway and is also considered a potential diagnostic and prognostic marker in THCA." (PMID 41602372, 2026). "ITGA10 mediates the activation of the PI3K/AKT pathway, which is associated with the proliferation and chemotherapy resistance of osteosarcoma." (PMID 41179658, 2025). "For example, ZIP10 stimulates the proliferation and chemoresistance of osteosarcoma cells by activating the PI3K/AKT pathway via ITGA10-mediated mechanisms." (PMID 38531930, 2024). "Previous studies have reported that ITGA10 promotes drug resistance and proliferation of osteosarcoma cells by the activation of PI3K/AKT signaling pathway." (PMID 36936416, 2023). "Similarly, ZIP10 can initiate CREB phosphorylation, activate the PI3K/AKT signaling pathway via ITGA10, and promote osteosarcoma cell proliferation and drug resistance." (PMID 40328750, 2025). "ITGA10 stimulates the PI3K/AKT signaling pathway and drives the proliferation and chemotherapy resistance of osteosarcoma cells." (PMID 41179658, 2025). "The PI3K/Akt pathway is considered one of the most important oncogenic pathways in human cancers, with ZIP10 driving osteosarcoma proliferation and chemoresistance through activation of the PI3K/AKT pathway mediated by ITGA10 and highly correlated with clinical prognosis." (PMID 39469643, 2024).
lung carcinoma (4 papers, 2015 to 2023). "In addition, dysregulation and carcinogenic effects of ITGA10 had been observed in lung cancer, prostate cancer, and thyroid cancer." (PMID 36936416, 2023). "In NSCLC patients, RUNX was more frequently methylated in tumor tissues than in noncancerous tissues.However, the functions of ITGA10 and ITPKB in lung cancer are still unknown." (PMID 26642205, 2015).
melanoma (4 papers, 2020 to 2021). A malignant, usually aggressive tumor composed of atypical, neoplastic melanocytes. "ITGA10 is associated with various cancers development and metastasis, and variants in ITGA10 are associated with changes of melanoma risks." (PMID 34660316, 2021). "And further investigation showed downregulating ITGA10 expression by an inhibitory antibody or an antisense construct had hindered migratory potential, suggesting a role for ITGA10 in melanoma cell migration." (PMID 33520460, 2021). "Some studies found that tissues with gene variants of ITGA10 and ITGA6 were less susceptible to melanoma." (PMID 33335550, 2020). "ITGA10 was also observed to b up-regulated in malignant melanoma cells." (PMID 33520460, 2021).
myxofibrosarcoma (4 papers, 2020 to 2024). A malignant fibroblastic neoplasm arising from the soft tissue. "Furthermore, ITGA10 can drive tumorigenesis in myxofibrosarcoma by promoting tumor cell survival through the activation of TRIO-RAC-RICTOR-mTOR signaling." (PMID 38017134, 2024). "A study analyzed the gene expression profile of 64 cases of primary myxofibrosarcoma and found that patients with high ITGA10 expression had a significantly worse prognosis, revealing that ITGA10 promotes tumor cell survival by activating TRIO/RICTOR signaling." (PMID 33335550, 2020). "A previous study showed that ITGA10 activates the RAC/PAK and AKT pathways in myxofibrosarcoma, and we thus evaluated the expression of these signaling molecules in OS cells with/without ITGA10 knockdown (ITGA10 siRNA; siITGA10)." (PMID 34706747, 2021).
skin cutaneous melanoma (4 papers, 2021 to 2023). "The expression levels of ITGA10, a biomarker of type II diabetes mellitus, are associated with metastasis in skin cutaneous melanoma." (PMID 36875704, 2023). "The signature genes CEACAM5, ITGA10 and MMP13 had the highest proportion of mutations among all 467 patients with cutaneous melanoma of the skin." (PMID 34675134, 2021). "Integrin subunit alpha 10 (ITGA10) is a receptor for collagen, has been supposed to be the prognostic biomarker for skin cutaneous melanoma and ovarian cancer." (PMID 37621558, 2023).
breast carcinoma (3 papers, 2015 to 2023). "Through the acquisition of adhesion ability, the integrins ITGB2, ITGB4, and ITGA10 may promote the attachment of breast cancer cells to the extracellular matrix and thereby enhance metastasis." (PMID 36910659, 2023).
chondrodysplasia (3 papers, 2013 to 2022). "Given the lack of intermediate phenotypes in the heterozygous dogs and the likely loss of all ITGA10 function in affected dogs, the corresponding human conditions would likely be recessive chondrodysplasias." (PMID 24086591, 2013). "Also, a truncated mutation in the cartilage-specific ITGA10 is known to cause chondrodysplasia in dogs." (PMID 36230363, 2022). "In summary, we identify a novel canine chondrodysplasia gene, ITGA10, which also represents a candidate gene for human chondrodysplasias." (PMID 24086591, 2013). "The canine chondrodysplasia phenotype implicates an essential role for ITGA10 in endochondral ossification and reveals a candidate gene for similar conditions in other species, including human." (PMID 24086591, 2013). "ITGA10 represents an excellent candidate gene for chondrodysplasia." (PMID 24086591, 2013).
ovarian carcinoma (3 papers, 2020 to 2024). A malignant neoplasm originating from the surface ovarian epithelium. "Integrin genes altered in 343 samples from 594 ovarian cancer patients (58%), of which ITGA10 genes accounted for the highest alteration frequency (12%)." (PMID 32765584, 2020).
dilated cardiomyopathy (2 papers, 2013 to 2025). Cardiomyopathy which is characterized by dilation and contractile dysfunction of the left and right ventricles. "Lamc3, for instance, was involved in the PI3K-Akt signaling pathway, while Tpm3 and Itga10 were associated with dilated cardiomyopathy." (PMID 40606020, 2025). "Moreover, in dilated cardiomyopathy pathway core enrichment, integrins (Itga1, Itga10, Itga8 and Itgb6) and cellular components of troponin system (Tnni3, Tnnc1 and Tnnt2) appeared modulated, besides Cox and Myh genes." (PMID 24252798, 2013).
glioblastoma (2 papers, 2019 to 2024). The most malignant astrocytic tumor (WHO grade IV). "It has been reported that ITGA10 can promote tumor growth and be successfully targeted by anti-ITGA10 antibodies in glioblastoma." (PMID 38017134, 2024). "Gene expression analysis of 48 well-characterized GBM cell lines from patient surgical samples (Human Glioblastoma Cell Culture (HGCC)) revealed expression of ITGA10 in all tested cell lines, although the expression levels varied between the different cell lines." (PMID 31027305, 2019).
osteoporosis (2 papers, 2018 to 2021). A condition of reduced bone mass, with decreased cortical thickness and a decrease in the number and size of the trabeculae of cancellous bone (but normal chemical composition), resulting in increased fracture incidence. "Studies have shown that ITGA10 can regulate the balance between osteogenesis and osteoclastogenesis and then rescue glucocorticoid-induced osteoporosis." (PMID 34794414, 2021).
asthma (1 paper, 2023). "The results showed that these 9 feature genes had good discrimination ability for asthma, with age, RNF182 and ITGA10 being the top three contributing factors." (PMID 36862916, 2023).
bladder urothelial carcinoma (1 paper, 2024). "In terms of alteration types, ITGA10 had high amplification rates in hepatocellular carcinoma (LIHC, 9.7%), BRCA (9.2%), and bladder urothelial carcinoma (BLCA, 9.0%), whereas it predominantly mutated in SKCM (7.8%)." (PMID 39436262, 2024).
cardiomyopathy (1 paper, 2021). A disease of the heart muscle or myocardium proper. "However, a downregulation of genes in the cardiomyopathy pathways, primarily characterized by genes from the alpha integrin family (ITGA10, ITGA11, ITGAB), which bind collagen and are involved in the degradation of the extracellular matrix, was observed." (PMID 34943818, 2021).
cholangiocarcinoma (1 paper, 2024). A carcinoma that arises from the intrahepatic biliary tree (intrahepatic cholangiocarcinoma) or from the junction, or adjacent to the junction, of the right and left hepatic ducts (hilar cholangiocarcinoma). "In terms of cancer types, ITGA10 and ITGA5 represented the most frequently amplified genes in cholangiocarcinoma (CHOL), whereas other integrin genes were rarely amplified." (PMID 39436262, 2024).
diabetes (1 paper, 2022). "This study found that ITGA10 expression was significantly lower in BMSCs from diabetic patients with implant failure than that in BMSCs from diabetic patients with implant success and normal patients without diabetes." (PMID 35635091, 2022).
fibrosis (1 paper, 2023). the formation of excess fibrous connective tissue in an organ or tissue in a reparative or reactive process. "Existing studies have shown that inhibition of macrophage migration inhibitory factor (MIF) can downregulate the expression level of ITGA10 and reduce bleomycin-induced pulmonary inflammation and fibrosis in rats." (PMID 36936416, 2023).
glioma (1 paper, 2019). A benign or malignant brain and spinal cord tumor that arises from glial cells (astrocytes, oligodendrocytes, ependymal cells). "Moreover, we show that high ITGA10 expression correlates with a worse overall survival probability in glioma patients and may play a critical role in tumor progression in glioma." (PMID 31027305, 2019). "When we analyzed the gene expression of ITGA10 using the cancer genome atlas (TCGA) dataset for low- (II) and high-grade gliomas (III and GBM), we found that ITGA10 expression significantly increased with the increasing tumor grade, supporting the protein expression results from the glioma tissues." (PMID 31027305, 2019).
leukemia (1 paper, 2014). A malignant (clonal) hematologic disorder, involving hematopoietic stem cells and characterized by the presence of primitive or atypical myeloid or lymphoid cells in the bone marrow and the blood. "Herein we show that in leukemia cells ERG overexpression promotes a mesenchymal-like gene expression signature that includes: CD24, CD44, ITGA10, ITGB5, ITGB3, ITGA2B and the morphogenic-associated genes, such as SHANK3, TYROBP." (PMID 24504051, 2014).
osteoarthritis (1 paper, 2023). A noninflammatory degenerative joint disease occurring chiefly in older persons, characterized by degeneration of the articular cartilage, hypertrophy of bone at the margins and changes in the synovial membrane. "Interestingly, ITGAV, ITGB1, and ITGA10 involve multiple chondrocyte subtypes, which suggests that they have a greater impact on the development of osteoarthritis." (PMID 37660146, 2023).
pulmonary fibrosis (1 paper, 2023). Chronic progressive interstitial lung disorder characterized by the replacement of the lung tissue by connective tissue, leading to progressive dyspnea, respiratory failure, or right heart failure. "The relationship between ITGA10 and MIF is still lacking relevant evidence and the future development of inhibitors targeting MIF may contribute to the treatment of pulmonary fibrosis." (PMID 36936416, 2023).
sarcoma (1 paper, 2020). A usually aggressive malignant neoplasm of the soft tissue or bone. "Transcript expression analysis showed that the two dominant transcripts of ITGA10 (ENST00000369304.7 and ENST00000539363.2) in TCGA sarcoma cases contain exon 1, suggesting that the promoter of ITGA10 transcription locates before this exon." (PMID 31742892, 2020).
small cell lung carcinoma (1 paper, 2015). Small cell lung cancer (SCLC) is a highly aggressive malignant neoplasm, accounting for 10-15% of lung cancer cases, characterized byrapid growth, and early metastasis. "Moreover, we performed dual luciferase reporter assay and Western blot on 6 targeted genes (FZD8, ITGA10, ITPKB, LRP5, PIAS1 andRUNX1) in small cell lung carcinoma cell line NCI-H82." (PMID 26642205, 2015).
Stroke (1 paper, 2024). Sudden impairment of blood flow to a part of the brain due to occlusion or rupture of an artery to the brain. "In both male and female stroke brains, we found that MMP-3 KO decreased the expression of Itga10 and Itgb3, which encode the subunits that form integrin αvβ3." (PMID 39000490, 2024). "Similarly, genes involved in integrin cell surface interactions including Itga10, Itgb3, Vcam1, Itgb1, Itgae, Itgb7, Itga1, Itga5, Icam1, Itgb2, Pecam1, and Icam2 were depleted in male MMP-3 KO stroke brains." (PMID 39000490, 2024).
tumor (19 papers, 2012 to 2025). "In high-grade MFS, it was shown that ITGA10 promotes tumor cell survival through the activation of TRIO-RAC-RICTOR-mTOR signaling, and is thus a potential therapeutic target." (PMID 35053609, 2022). "Although recent studies have suggested that ITGA10 may be involved in regulating tumor progression, the expression and role of ITGA10 in OS cells have not yet been reported." (PMID 34706747, 2021). "ITGA10 transmitted specific signals through TRIO and RICTOR, activating RAC/PAK and AKT/mTOR pathways to promote tumor cell survival." (PMID 40258773, 2025). "COL17A1, ITGA10 and MMP7 showed high intertumoral heterogeneity between tumor tissues and adjacent tissues." (PMID 36936416, 2023). "HLTF, ITGA10, PLCG1, and TTC3 are potential tumor antigens of STS for the development of mRNA vaccines." (PMID 35053609, 2022). "In univariate analysis, larger tumour size, with pharmaceutical drug adjuvant therapy, high FNCLCC grade, increased COL11A1, ITGA10 and KIF26B expression, and decreased CLEC3B, DUOX2, KRT75 and PPP2R2B were risk factors of shorter RFS." (PMID 31742892, 2020). "Finally, four potential tumor antigens were identified, each related to prognosis and antigen-presenting cell infiltration in STS: HLTF, ITGA10, PLCG1, and TTC3." (PMID 35053609, 2022). "Although the activity of increased expression of Itga10 by GLSF is unknown, the interaction of integrin and collagen may mediate an anti-tumor immune response." (PMID 35692861, 2021). "For example, CP and ITGA10 were upregulated exclusively in GFP+ versus DsRed+ tumor cells but not at all by in vitro exposure to hypoxia." (PMID 31649238, 2019). "Many of these genes, including those encoding bFGF, MAPK10, MAP3K5, IL1R2, E-cadherin, Ki67, Cyclin E1, beta-catenin, 14-3-3 protein T-cell (YWHAQ), integrin alpha-V (ITGAV), integrin alpha-10 (ITGA10), CDK6, PCNA, CDKN1A, and PAK3, are related to tumor metastasis and regulation of cell migration." (PMID 28454092, 2017). "To determine whether ZIP10, p-CREB, ITGA10 and p-AKT levels correlate in OS, we collected 52 patient tumor tissue sections without chemotherapy." (PMID 34706747, 2021).
cancer (8 papers, 2019 to 2024). A tumor composed of atypical neoplastic, often pleomorphic cells that invade other tissues. "Interestingly, ITGA10, encoding the α10 integrin, is the most amplified gene in a number of cancers, and consistent with this genomic alteration, it is consequently dysregulated in the majority of cancers." (PMID 34715893, 2021). "Consistently, the gene expression of collagen I receptors, linked to active tissue remodeling and cancer, including DDR2, ITGA2, ITGA10, ITGA11 and ITGB1 was higher in OS compared to RMS, whilst DDR1 expression was higher in RMS tumors." (PMID 35957513, 2022). "To gain a better understanding of the potential roles played by individual integrins in different cancer-contexts, we chose ITGA10 and ITGA1 for further analysis in detail." (PMID 34715893, 2021). "This highlights that ITGA10 functions in a cancer-specific manner." (PMID 34715893, 2021). "In the next step, a comparison analysis using the cancer genome atlas (TCGA) PCa datasets confirmed elevated CLDN7, COL8A1, and ITGA10 mRNA expression in PCa tissue samples." (PMID 38017134, 2024). "Firstly, the biological mechanisms of COL14A1, COL17A1, ITGA10 and MMP7 in IPF and cancer are still unclear." (PMID 36936416, 2023).
ITGA10 also shares sentences with these, for which no sentence is quoted: dwarfism (2 papers); breast invasive carcinoma (1); colon cancer (1); cutaneous squamous cell carcinoma (1); hepatocellular carcinoma (1); human papillomavirus infection (1); inflammation (1); lobular carcinoma (1); neuroblastoma (1); neurological disorders (1); oropharyngeal squamous cell carcinoma (1); polyp (1); prostate carcinoma (1); thyroid cancer (1); type 2 diabetes mellitus (1).